WDR5 (WD repeat domain 5)
Diseases named in the same sentence as WDR5 in open-access papers (continued):
Sharing a sentence is not in itself a finding about the gene and the disease.
glioblastoma (5 papers, 2023 to 2026). The most malignant astrocytic tumor (WHO grade IV). "Essentiality of WDR5 together with ASH2L for glioblastoma cells emphasizes the importance of WRAD module for cancer cell fitness." (PMID 37974198, 2023). "To assess the functional importance of SET1/MLL family complex members for glioblastoma cell viability, we performed siRNA mediated knock-down of WDR5 and KMT2A (MLL1) in U373 and U87MG cells and checked their colony forming ability." (PMID 37974198, 2023). "Mitchell and colleagues addressed the critical roles of POU5F1 in WDR5-induced glioblastoma progression." (PMID 37325625, 2023). "The growing experimental data indicate that WDR5 also might be a therapeutic target for lung adenocarcinoma, squamous cell carcinoma, and glioblastoma." (PMID 39201460, 2024). "N-MYC is overexpressed in subsets of glioblastoma and therefore some of the findings in this study may be applicable to understanding the totality of how WDR5 inhibition impacts glioblastoma growth and function." (PMID 37336886, 2023). "We observed that glioblastoma cells had differential dependency to SET1/MLL family of epigenetic factors, since cells showed differential response to MLL1 and WDR5 ablations." (PMID 37974198, 2023). "WDR5 is best known for its role in promoting the assembly of MLL/SET methyltransferase complexes through its physical interactions within the WRAD (WDR5–RBBP5–ASH2L–DPY30) complex, which has been shown to be important in multiple cancers such as leukemia and glioblastoma." (PMID 37336886, 2023).
glioma (4 papers, 2016 to 2024). A benign or malignant brain and spinal cord tumor that arises from glial cells (astrocytes, oligodendrocytes, ependymal cells). "Investigation of its subunits WDR82, ASH2L DPY30 CXXC1, RBBP5, and WDR5 showed that WDR82 and WDR5 were significantly associated with WHO-grade malignancy in pediatric gliomas." (PMID 37444539, 2023). "In human glioma, PRMT5 facilitates the enrichment of H3R2me1 and H3R2me2s, recruiting WD repeat domain 5 (WDR5) to promote H3K4 methylation at the VEGFA promoter, thereby enhancing its transcription." (PMID 39519130, 2024). "WDR5 is a well-known chaperone of PHF20 and has been reported to function as an oncogene in many cancers, including glioma." (PMID 33117706, 2020).
lung carcinoma (4 papers, 2022 to 2024). "Protein interaction between WDR5/MLL3 and MLL3/P300 revealed a WDR5/MLL3/P300 complex that stabilized by MIR31HG in lung cancer cells." (PMID 37950038, 2024). "Our findings that lncRNA MIR31HG stimulates GLI2 by WDR5/MLL3/P300-mediated active chromatin landscape highlight lncRNA MIR31HG as a potential target for clinical lung cancer clinic treatment." (PMID 37950038, 2024). "WD repeat domain 5 (WDR5) has been reported to serve as a bridge protein to assist mono-, di-, and tri-methylation in H3K4, initiating cancer stem-like properties such as drug resistance and metastasis of lung cancer cells." (PMID 37950038, 2024). "In a lung cancer cell, H4K5 acetylation and H3K4 trimethylation induced by sodium 4-phenylbutyrate (4PBA) were replaced by TXNIP-dependent sodium butyrate (NaBu) as they promote the WDR5 expression leading to the initiation of caspase 3/7 and induction of apoptosis." (PMID 36366411, 2022).
acute lymphoblastic leukemia (3 papers, 2018 to 2024). Leukemia with an acute onset, characterized by the presence of lymphoblasts in the bone marrow and the peripheral blood. "A study revealed that WD repeat-containing protein 5 (WDR5), a core subunit involved in H3K4 methylation, could affect the metastasis of acute lymphoblastic leukemia (ALL) cells in dense 3D conditions." (PMID 39768219, 2024).
Burkitt lymphoma (3 papers, 2020 to 2025). A rare form of malignant mature B-cell non-Hodgkin lymphoma. "One such cofactor is the chromatin regulator WDR5, which in models of Burkitt lymphoma facilitates recruitment of the c-MYC protein to chromatin at genes associated with protein synthesis, allowing for tumor progression and maintenance." (PMID 37336886, 2023). "Other studies have identified the interaction of MYC with WDR5 via the MBIIIb region of the MYC TAD as critical for recruitment of MYC to chromatin, including in Burkitt lymphoma." (PMID 40721291, 2025). "However, beyond Burkitt lymphoma, it is unknown whether these observations extend to other cancers or MYC family members, and whether WDR5 can be deemed as a “universal” MYC recruiter." (PMID 37336886, 2023). "An inducible exon swap system in a Burkitt lymphoma cell line was created to study the interaction between Myc and WDR5 by implementing a mutant Myc that could not interact with WDR5." (PMID 33322239, 2020).
Kabuki syndrome (3 papers, 2017 to 2024). Kabuki syndrome (KS) is a multiple congenital anomaly syndrome characterized by typical facial features, skeletal anomalies, mild to moderate intellectual disability and postnatal growth deficiency. "Dysfunctional WDR5 due to genetic mutations is particularly linked to Kabuki syndrome and Kleefstra syndrome characterized by ID." (PMID 36743289, 2022). "These include Coffin-Siris syndrome (ARID1B), Koolen-de Vries syndrome (KANSL1), Kabuki syndrome (WDR5), and Kleefstra syndrome (WDR5)." (PMID 36743289, 2022). "KMT2D and WDR5 defects are involved in Kabuki Syndrome characterized by multiple congenital abnormalities, from mild to severe developmental delay and intellectual disability." (PMID 28993790, 2017).
colitis (2 papers, 2023 to 2025). Inflammation of the colon. "Interestingly, long noncoding (lnc) RNA PTPRE‐AS1 bound WDR5 directly, thereby modulating H3K4me3 of the PTPRE promoter to modulate PTPRE‐dependent signaling during M2 macrophage activation, which is involved in inflammatory diseases, including reducing chemical‐induced colitis." (PMID 40586619, 2025).
colorectal tumor (2 papers, 2017 to 2023). "In addition, WDR5 mRNA expression was markedly higher in colorectal tumor tissues than those in paired adjacent normal mucosal tissues (qRT-PCR; n=16; P<0.05)." (PMID 28300833, 2017). "Consistently, the expressions of genes related to cancer stem-like traits were increased in the colorectal tumors of OXA treatment mice, compared to NS treatment mice, including TOX3, WDR5, and ABCG2." (PMID 37708089, 2023).
embryonal carcinoma (2 papers, 2014 to 2024). A non-seminomatous malignant germ cell tumor characterized by the presence of large germ cells with abundant cytoplasm resembling epithelial cells, geographic necrosis, high mitotic activity, and pseudoglandular and pseudopapillary structures formation. "In P19 embryonal carcinoma cells, the retinoic acid-induced Hox expression was further stimulated by Rnf220 knockdown, which can also be rescued by Wdr5 knockdown." (PMID 39526890, 2024). "To study the impact of MLL/COMPASS on DNA methylation, we targeted WDR5, a component essential for all MLL/COMPASS complexes to bind the histone H3 N-terminal tail, for siRNA-mediated depletion using the human embryonic carcinoma cell line (ECC) NCCIT as a model system." (PMID 25071008, 2014).
epilepsy (2 papers, 2024 to 2026). A brain disorder characterized by episodes of abnormally increased neuronal discharge resulting in transient episodes of sensory or motor neurological dysfunction, or psychic dysfunction. "Intriguingly, a recent study identified epilepsy as a highly penetrant phenotype in 11 unrelated individuals carrying WDR5 missense mutations, suggesting potential dominant-negative or gain-of-function mechanisms." (PMID 41510154, 2026). "Interestingly, a previous study in patients suggested a potential association of Arid5b with epilepsy 46, suggesting that Arid5b may be a direct target of WDR5-H3K4me3 under epileptic conditions." (PMID 41510154, 2026). "Collectively, these results demonstrate that neuron-targeted WDR5 knockdown preferentially modulates postsynaptic mechanisms to rebalance E/I synaptic transmission and alleviate network hyperexcitability in epilepsy." (PMID 41510154, 2026). "While our study does not directly address inherited epigenetic marks, the sustained dysregulation of the WDR5/H3K4me3 axis described herein may represent a form of "epigenetic memory" that contributes to long-term epilepsy vulnerability." (PMID 41510154, 2026). "This increased assembly of the WDR5-KMT2 complex may be attributed to the elevated expression of both WDR5 and KMT2 family members in the hippocampus following epilepsy induction." (PMID 41510154, 2026).
heart failure (2 papers, 2022 to 2024). Inability of the heart to pump blood at an adequate rate to meet tissue metabolic requirements. "To evaluate the Wdr5 effect on cardiac function, we believe that further investigation should be tested in heart failure models (such as transverse aortic constriction, TAC)." (PMID 36358925, 2022). "Together with the results of the present study, these findings suggest that WDR5/MLL1 may also be a target for the amelioration of cardiac fibrosis and heart failure." (PMID 38503742, 2024).
Hepatic fibrosis (2 papers, 2025). The presence of excessive fibrous connective tissue in the liver. "Consequently, WDR5 is recruited by different RNA‐binding proteins and lncRNAs to the promoter region of the downstream targets, thereby enabling H3K4me3 modification and transcriptional activation in varying inflammatory diseases, including liver fibrosis and Alzheimer's disease." (PMID 40586619, 2025).
Intellectual disability (2 papers, 2017 to 2023). "WDR5 plays a crucial role in regulating neuronal gene expression and neurite outgrowth and contributes to the development of X chromosome-linked mental retardation." (PMID 36674445, 2023).
lymph node metastases (2 papers, 2021 to 2023). "In addition, overexpression of WDR5 was found in patients with lymph node metastases from cohort 1 and TCGA cohort." (PMID 33754029, 2021). "The increased TOX3, WDR5, and ABCG2 expression was respectively detected in the majority of metastatic CRCs as compared with those with no lymph node metastasis." (PMID 37708089, 2023).
melanoma (2 papers, 2016 to 2024). A malignant, usually aggressive tumor composed of atypical, neoplastic melanocytes. "WDR5 target RAB28, member of the Ras oncogene family, is reported to be differentially expressed in swine melanoma." (PMID 27192115, 2016).
pancreatic ductal adenocarcinoma (2 papers, 2018 to 2020). An infiltrating adenocarcinoma that arises from the epithelial cells of the pancreas. "Mechanistically, WDR5 interacts with c-Myc to sustain proper DNA replication, and is essential for pancreatic ductal adenocarcinoma cell proliferation, tumor initiation, and progression." (PMID 30488017, 2018). "Through screening patient-derived pancreatic ductal adenocarcinoma xenografts or genetically engineered mouse model-derived allografts, WDR5 has been found to be a top tumor maintenance gene for, and considerably over-expressed in, human pancreatic ductal adenocarcinomas." (PMID 30488017, 2018). "In pancreatic ductal adenocarcinoma cells, OICR-9429 blocks WDR5-c-Myc protein complex formation and effectively reduces tumor cell clonogenic capacity." (PMID 30488017, 2018).
pulmonary fibrosis (2 papers, 2023 to 2025). Chronic progressive interstitial lung disorder characterized by the replacement of the lung tissue by connective tissue, leading to progressive dyspnea, respiratory failure, or right heart failure. "To validate the specific role of inhibiting the interaction between KMT2A and WDR5 in the development of pulmonary fibrosis, we administered the KMT2A competitive inhibitor mm102 as an intervention treatment in a pulmonary fibrosis mouse model." (PMID 39888275, 2025).
renal fibrosis (2 papers, 2022 to 2025). A final common manifestation of a wide variety of chronic kidney diseases characterized by glomerulosclerosis and tubulointerstitial fibrosis. "Inhibition of Wdr5 and its methyltransferase activity attenuated renal fibrosis and inflammation in the kidney with ischemia-reperfusion injury, and it is involved in renal fibrosis in diabetic nephropathy." (PMID 36358925, 2022). "Our research has demonstrated that the inhibition of MLL1 and WDR5—via MM-102 and OICR-9429, respectively—as well as siRNA targeting MLL1/WDR5 complex, reduces p16INK4a expression and H3K4 tri-methylation in a mouse model of IRI-induced renal fibrosis." (PMID 40186651, 2025).
triple-negative breast carcinoma (2 papers, 2022 to 2024). An invasive breast carcinoma which is negative for expression of estrogen receptor (ER), progesterone receptor (PR), and human epidermal growth factor receptor 2 (HER2). "Inhibition of WDR5 and mTOR cooperatively reduces translation and triple-negative breast cancer (TNBC) cell growth." (PMID 36043466, 2022). "Using an in vivo genetic screen, we identified WDR5 as an actionable epigenetic regulator that is required for metastatic progression in models of triple-negative breast cancer." (PMID 36043466, 2022).
viral infection (2 papers, 2012 to 2022). "It is known that viral infection leads to a decrease in the expression level of WDR5 in the nucleus as observed in HAM/TSP." (PMID 35041720, 2022). "It has previously been reported that WDR5 is more abundant in the cytoplasm than in the nucleus of human embryonic kidney 293 cells, and that it can be translocated from the nucleus to the cytoplasm during viral infection." (PMID 22523547, 2012).
acute leukemia (1 paper, 2016). A clonal (malignant) hematopoietic disorder with an acute onset, affecting the bone marrow and the peripheral blood. "Here, we reported the WDR5 high expression in human acute leukemia and WDR5-mediated H3K4 methylation of oncogenic targets may play an important role in leukemogenesis." (PMID 27192115, 2016).
asthma (1 paper, 2025). "pDCs downregulate IFN-I through aberrant histone methylation, such as WDR5-mediated inhibition of H3K4 trimethylation, which compromises their antiviral capacity and elevates the risk of infections during asthma treatment." (PMID 41246337, 2025).
breast tumour (1 paper, 2015). "MCF7 has been previously applied with a success to explore the effect of MLL2 depletion on breast tumour cell growth, and the association of reduced breast tumour cell proliferation with WDR5 deficiency has been previously demonstrated using western blot in MCF7." (PMID 26355959, 2015). "We focused on the prognostic value of WDR5 expression on breast tumour survival in this study, and particularly analyzed ER positive tumours in BreastMark." (PMID 26355959, 2015). "IC50 values do not significantly differ between siRNA-transfected cells and controls, suggesting that WDR5 deficiency does not affect the drug response of breast tumour cells to doxorubicin." (PMID 26355959, 2015). "As a core subunit of MLL and SET1 histone H3K4 methyltransferase complexes, WDR5 is required for complex assembly and methyltransferase activity, which may be a newly identified coactivator whose expression is under long-range regulation during breast tumour progression." (PMID 26355959, 2015). "Also, we will investigate whether WDR5 expression affects the response of cells to hormone treatment, for which experimental approaches such as studies on tamoxifen-treated ER positive breast tumour cells before and after knocking down WDR5 would be appropriate." (PMID 26355959, 2015).
ciliopathies (1 paper, 2024). "Among 8 probands, we identified 12 variants in 7 genes associated with ciliopathies including Joubert syndrome (KIAA0586, ARMC4, BBS1, CEP83, ARMC9, TOGARAM1, WDR5)." (PMID 38585811, 2024).
co-infection (1 paper, 2015). "Such co-infection, however, did not increase the effect on Dpy30 and Wdr5 expression." (PMID 26691508, 2015).
colorectal adenocarcinoma (1 paper, 2017). The most common type of colorectal carcinoma. "Moreover, similar results can be counted in large samples from TCGA Colorectal Adenocarcinoma (COADREAD) that project that about twofold greater WDR5 mRNA expression levels were calculated in human CRC tissues than in normal tissues (P<0.001)." (PMID 28300833, 2017).
colorectal adenoma (1 paper, 2022). An adenoma that arises from the colon or rectum. "Consistently, transcriptome analysis results showed that the expression levels of CDK1 correlated well with those of WDR5 in colorectal adenomas (GSE8671)." (PMID 35371306, 2022).
fibrosis (1 paper, 2022). the formation of excess fibrous connective tissue in an organ or tissue in a reparative or reactive process. "Taken together, we identified Wdr5 as a key epigenetic regulator that promotes cardiac fibrosis and FMT." (PMID 36358925, 2022). "The effects of Wdr5 on the cardiac fibrosis phenotype and the activation or transformation of cardiac fibroblasts were investigated by Ang-II-infused mice by osmotic mini-pump and isolated primary neonatal rat cardiac fibroblasts." (PMID 36358925, 2022).
head and neck squamous cell carcinoma (1 paper, 2025). A squamous cell carcinoma that arises from any of the following anatomic sites: lip and oral cavity, nasal cavity, paranasal sinuses, pharynx, larynx, and salivary glands. "In head and neck squamous cell carcinoma (HNSCC), PRMT5-mediated H3R2me2s facilitates the recruitment of the MLL/SET1/WDR5 complex to the TWIST1 promoter, increasing H3K4me3 and TWIST1 transcription, thereby promoting EMT and lymph node metastasis." (PMID 41204384, 2025).
Hyperglycemia (1 paper, 2022). An increased concentration of glucose in the blood. "We detected a significant increase in MLL2 and WDR82 in HUVEC exposed to intermittent hyperglycemia, and such treatment did not alter the protein level expression of SET1A, WDR5, SET1B, and MLL1(NT)." (PMID 35392173, 2022).
lymphoid leukemia (1 paper, 2024). A malignant lymphocytic neoplasm of B-cell or T-cell lineage involving primarily the bone marrow and the peripheral blood. "For example, the lncRNA HOTTIP derived from the HOXA locus directly interacts with WD repeat-containing protein 5 (WDR5), thereby guiding the histone methyltransferase complex WDR5-MLL (myeloid/lymphoid leukemia) to the promoters of HOXA genes to promote gene transcription." (PMID 39188306, 2024).
malaria (1 paper, 2024). Malaria is a serious and sometimes fatal disease caused by a parasite that commonly infects a certain type of mosquito which feeds on humans. "Targeting H3K4 methylation with WDR5 antagonists can be useful in controlling excessive inflammatory TNF and IL-6 production and thereby managing the pathogenesis of severe malaria." (PMID 38316918, 2024).
oral squamous cell carcinoma (1 paper, 2025). "WDR5, a member of the WD40 protein family, up-regulates expression in oral squamous cell carcinoma (OSCC), and silencing WDR5 can inhibit the occurrence of OSCC, and it might be a target for OSCC treatment." (PMID 39980564, 2025).
osteoporosis (1 paper, 2020). A condition of reduced bone mass, with decreased cortical thickness and a decrease in the number and size of the trabeculae of cancellous bone (but normal chemical composition), resulting in increased fracture incidence. "As to osteoporosis, the INO80 chromatin remodeling complex interacts with WD repeat-containing protein 5 (Wdr5) protein that catalyzes H3K4me3 formation to positively regulate the canonical Wnt pathway." (PMID 32963550, 2020).
papillary thyroid carcinoma (1 paper, 2023). "The expression of WD repeat domain 5 (WDR5) is relevant to papillary thyroid carcinoma progression and reduced prognosis." (PMID 36741260, 2023).